BRME1 (break repair meiotic recombinase recruitment factor 1)
Description:
Meiotic recombination factor component of recombination bridges involved in meiotic double-strand break repair. Modulates the localization of recombinases DMC1:RAD51 to meiotic double-strand break (DSB) sites through the interaction with and stabilization of the BRCA2:HSF2BP complex during meiotic recombination. Indispensable for the DSB repair, homologous synapsis, and crossover formation that are needed for progression past metaphase I, is essential for spermatogenesis and male fertility.
Synonyms: C19orf57; MGC11271; MEIOK21
Tractability: No criterion of Open Targets' tractability assessment is met for any kind of drug.
Gene: Protein-coding gene on chromosome 19 (13,882,343 to 13,906,572, reverse strand). Ensembl gene ENSG00000132016.
Subcellular location: Chromosome
Subcellular location (Human Protein Atlas): Nucleoplasm
Gene Ontology:
Molecular function: protein binding
Biological process: double-strand break repair involved in meiotic recombination; female meiosis I; spermatogenesis
Cellular component: chromosome
Genetic constraint (gnomAD): Loss-of-function variants: 32 observed, 52.83 expected, observed/expected ratio (o/e) 0.61, 90% interval 0.46 to 0.81. The upper end of that interval is the gene's LOEUF score, 0.81, which puts it in group 3 of 6, group 1 being the genes least tolerant of losing a copy. Missense variants: 804 observed, 867.67 expected, observed/expected ratio (o/e) 0.93, 90% interval 0.87 to 0.98. Synonymous variants: 359 observed, 357.51 expected, observed/expected ratio (o/e) 1, 90% interval 0.92 to 1.1.
Homologues: Orthologues: chimpanzee BRME1 (99% identical), macaque BRME1 (74% identical), rat Brme1 (38% identical), mouse Brme1 (36% identical), dog BRME1 (22% identical).
Diseases named in the same sentence as BRME1 in open-access papers:
BRME1 is named in the same sentence as 9 diseases in open-access papers, as found by Europe PMC text mining. Sharing a sentence is not in itself a finding about the gene and the disease. The quoted sentences say what the papers report.
cervical cancer (2 papers, 2022 to 2023). A primary or metastatic malignant neoplasm involving the cervix. "Unsupervised hierarchical clustering yielded a striking natural division of HNSCC PDXs by HPV status, with C19orf57 (BRME1), a gene previously correlated with positive response to cisplatin in cervical cancer, among the most significantly differentially expressed genes between HPV+ and HPV- PDXs." (PMID 36857322, 2023).
infertile (1 paper, 2020). "Although Brme1−/− mice showed no apparent somatic phenotypes, Brme1−/− males, but not females, were infertile similar to Meilb2−/− mice." (PMID 32345962, 2020).
cancer (5 papers, 2020 to 2024). A tumor composed of atypical neoplastic, often pleomorphic cells that invade other tissues. "MEILB2 and BRME1 are highly expressed in many human cancer tissues with a similar expression pattern." (PMID 34440403, 2021). "BRME1 is upregulated in a number of human cancer tissues, and its cancer type-specific expression pattern is reminiscent of that of MEILB28." (PMID 32345962, 2020). "Given that MEILB2 and BRME1 are also aberrantly expressed in human cancer cell lines, the amplification of gene products involved in BRCA2 function and subsequent hijacking of the intrinsic HR pathway might be a driving force in the development of certain sporadic cancers." (PMID 32345962, 2020).
BRME1 also shares sentences with these, for which no sentence is quoted: tumor (2 papers); cervical squamous cell carcinoma (1); endocervical adenocarcinoma (1); male infertility (1); oropharyngeal squamous cell carcinoma (1); ovarian insufficiency (1).